GPX8 (glutathione peroxidase 8 (putative))
Diseases named in the same sentence as GPX8 in open-access papers (continued):
Sharing a sentence is not in itself a finding about the gene and the disease.
colon cancer (2 papers, 2022). "So, as the presence of GPx8 in the plasma inside the cross-section of vessels in specimens of healthy tissue was found in our research, in the future, this point could be explored as the prognostic marker of the beginning stages of inflammatory diseases or for colon cancer risk assessment." (PMID 35208621, 2022). "Moreover, the result of CPTAC analysis demonstrated the protein expression of GPX8 was up-regulated and correlated with the pathological stages of colon cancer, clear cell RCC, LUAD and UCEC." (PMID 35402257, 2022). "From this point of view, GPx8 is even more important than GPx4, which is absent in the mucosa of almost 71% of cases of colon tumors." (PMID 35208621, 2022).
colorectal adenocarcinoma (2 papers, 2022 to 2025). The most common type of colorectal carcinoma. "This study investigated the potential of GPX8 as a prognostic marker in patients with gastric and colorectal adenocarcinoma." (PMID 39833079, 2025). "On the other hand, a positive immunohistochemical reaction against GPx4 only in 41.4% and against GPx8 only in 29.3% of human colorectal adenocarcinoma specimens were observed." (PMID 35208621, 2022). "The results showed that the expression level of GPX8 was significantly higher in STAD and colorectal adenocarcinoma tumor tissues compared to normal tissues, but significantly lower in READ (P < .01)." (PMID 39833079, 2025). "Subsequently, GPX8 expression was further explored in STAD, colorectal adenocarcinoma, and paracancer tissues in the TNMplot database." (PMID 39833079, 2025). "This study explored the expression of GPX8 in patients with STAD and colorectal adenocarcinoma, and its relevance to patient prognosis, utilizing clinical sample analysis, bioinformatics databases, and statistical methods." (PMID 39833079, 2025).
hepatocellular carcinoma (2 papers, 2024). A malignant tumor that arises from hepatocytes. "The suppression of glutathione peroxidase-8 (GPx8) enhances ER stress and cell death induced by oxidative stress in hepatocellular carcinoma cells; notably, GPx8 is transcriptionally regulated by HIF-1α." (PMID 39594520, 2024).
non-small cell lung carcinoma (2 papers, 2022). A group of at least three distinct histological types of lung cancer, including non-small cell squamous cell carcinoma, adenocarcinoma, and large cell carcinoma. "GPX8 is an endoplasmic reticulum-resident protein that plays an important role in various cancers, such as gastric, breast and non-small cell lung cancer." (PMID 35456975, 2022).
acute myeloid leukemia (1 paper, 2022). Acute myeloid leukemia (AML) is a group of neoplasms arising from precursor cells committed to the myeloid cell-line differentiation. "According to the result, GPX8 was upregulated in the kidney, cholangio, lymph gland, esophagus, brain, pancreas, skin, stomach, and thymus cancers and downregulated in acute myeloid leukemia." (PMID 36061208, 2022).
brain tumors (1 paper, 2023). "In the present work, the gene expression of gpx1 to gpx8 in brain tissue from animals with brain tumors induced by the transplacental administration of N-ethyl-N-nitrosourea (ENU) is analyzed in both male and female animals and compared with equivalent brain tissue from healthy animals." (PMID 37761814, 2023).
endometrial cancer (1 paper, 2025). Primary or metastatic malignant neoplasm involving the endometrium (mucous membrane that lines the endometrial cavity). "In contrast, GPX8 shows high expression in most cancers, including endometrial cancer." (PMID 39926275, 2025).
kidney tumors (1 paper, 2023). "First, GPX8 mRNA expression proportionally increased according to the grades of kidney tumors, which was confirmed at the protein level with an independent large proteomic database (CPTAC)." (PMID 36750850, 2023).
liver cancer (1 paper, 2024). An epithelial or non-epithelial malignant neoplasm that arises from the liver. "Further analysis indicated that patients with advanced clinical characteristics, such as tumor size larger than 5 cm, Barcelona Clinic Liver Cancer Stage B, and positive microvascular invasion, had significantly higher percentages of GPX8 low expression." (PMID 38607517, 2024).
low grade glioma (1 paper, 2022). A grade I or grade II glioma arising from the central nervous system. "For example, GPX1 expression was a potential prognostic factor in low-grade glioma (LGG) and so was GPX8 in GBM/LGG, based on bioinformatic analysis from TCGA." (PMID 36052280, 2022).
melanoma (1 paper, 2021). A malignant, usually aggressive tumor composed of atypical, neoplastic melanocytes. "Similar to our results, HDAC inhibitors reduced the expression of GPX8 protein in fibroblasts derived from a Niemann–Pick type C patient and Gpx8 mRNA in SK-MEL-3 melanoma cells." (PMID 34679638, 2021).
pancreatic cancer (1 paper, 2025). "GPX8 plays a role in radiation treatment—knockdown of GPX8 in BxPC-3 pancreatic cancer cells enhances radiation sensitivity." (PMID 40563487, 2025).
prostate adenocarcinoma (1 paper, 2022). "In addition, GPX8 was downregulated in kidney chromophobe, prostate adenocarcinoma, thyroid carcinoma, and uterine corpus endometrial carcinoma." (PMID 36061208, 2022).
skin carcinoma (1 paper, 2024). "The GPx8 somatic mutation with the least energy change is S157F (ΔΔG = −1.23 kcal/mol) and was discovered in patients with skin carcinoma." (PMID 39796732, 2024).
ulcerative colitis (1 paper, 2022). An inflammatory bowel disease involving the mucosal surface of the large intestine and rectum. "In patients with ulcerative colitis, the level of GPx8 in the macrophages of their colon tissue was reduced, and the level of caspase-4/11 was increased." (PMID 35208621, 2022).
cancer (26 papers, 2018 to 2025). A tumor composed of atypical neoplastic, often pleomorphic cells that invade other tissues. "Further studies are needed to explore the underlying mechanisms of GPX8 and its potential as a therapeutic target for these cancers." (PMID 39833079, 2025). "Beyond cancer, GPX8 has also been implicated in immune regulation, viral pathogenesis, and metabolic diseases." (PMID 40563487, 2025). "In a series of bioinformatics analyses, GPX8 was identified as a key prognostic gene expressed in cancer-associated fibroblasts (CAFs), playing a crucial role in the tumor microenvironment of lung adenocarcinoma." (PMID 39125992, 2024). "This suggests a potential role of these mutations in compromising the stability and function of GPx8, potentially contributing to the development and progression of associated cancers." (PMID 39796732, 2024). "The current research underscores the critical need for exploring the role of the endoplasmic reticulum-associated protein GPX8 in cancer biology." (PMID 38607517, 2024). "To summarize, the Survival and ROC curve analyses indicated that GPX8 was a valuable diagnostic biomarker in multiple types of cancers, including GBM/LGG, KIRC, KIRP and STAD." (PMID 35402257, 2022). "Subsequently, the results of TIMER, TIDE, XCEL, MCPCOUNTER, EPIC algorithms indicated a positive correlation between the GPX8 expression and cancer-associated fibroblast in many human cancers, including GBM, LGG, KIRC, KIRP and STAD." (PMID 35402257, 2022). "Glutathione peroxidase 8 (GPX8), located in the endoplasmic reticulum, is associated with poor prognosis in several cancers." (PMID 36061208, 2022). "Additionally, we assessed the localization of α-SMA (a biomarker for cancer-associated fibroblasts) and GPX8 through immunofluorescence in LUAD specimens." (PMID 38515109, 2024). "Interestingly, apart from the enrichment of cancer-associated fibroblasts in GPX8 high expression TMEs, we also found the active expression of the epithelial-mesenchymal transition (EMT) program." (PMID 38515109, 2024). "Furthermore, the receiver operating characteristic (ROC) curve was emplored to verify the diagnostic value of GPX8 in different cancers." (PMID 35402257, 2022). "Herein, our result demonstrated that the GPX8 expression might be related to cancer-associated fibroblasts and immune infiltration levels in certain tumors." (PMID 35402257, 2022). "Additionally, it is crucial to recognize that mutations in other genes might also play a role in the development of cancers linked to GPx7 and GPx8, underscoring the complexity of the genetic factors involved." (PMID 39796732, 2024). "In addition, GPx-8 is linked to various sorts of human malignant tumors." (PMID 37761814, 2023). "Nonetheless, the study provides important insights into the biology of these cancers and identifies GPX8 as a potential therapeutic target for future research." (PMID 39833079, 2025). "Univariate Cox analysis was performed to explore the relationship between GPX8 expression, immune cell levels, and the prognosis in cancer patients." (PMID 39833079, 2025). "Bosello found that there is a link between GPX8 and epithelial–mesenchymal transition (EMT), which is associated with cancer metastasis." (PMID 40563487, 2025). "Furthermore, the association between GPX8 and tumor-infiltrating lymphocytes in the tumor microenvironment, as well as the biological functions of GPX8 were also investigated, providing valuable insights into personalized treatment strategies for cancer patients." (PMID 39833079, 2025). "Ren observed the role of GPX8 in cancer immunology, highlighting its potential implications in the immune response." (PMID 40563487, 2025). "Glutathione peroxidase-8 (GPX8), a member of the glutathione peroxidase family, emerges as a potential target for intervention in the treatment of various cancers." (PMID 39833079, 2025).
cancer (continued). "Further research is needed to fully understand the role of GPX8 in cancer and its potential as a therapeutic target or prognostic marker." (PMID 39833079, 2025). "To clarify the function of GPX8 in cancer, we explored GPX8 expression in 21 different cancers in a pan-cancer analysis." (PMID 39833079, 2025). "Similar to GPX8, high Rho/RAC family expression is strongly associated with cancer mesenchymalization, metastasis, and stemness." (PMID 40562790, 2025). "The studies of the functions of GPx5, GPx6, GPx7, and GPx8 in cancer development are limited in comparison with those of Gpx1–Gpx4." (PMID 39125992, 2024). "GPx8 has been recognized as a prognostic marker for cancers such as primary glioma and gastric cancer." (PMID 39125992, 2024). "As expected, TME signatures such as cancer-associated fibroblast, matrix, matrix remodeling, and EMT signature rose with a gradual rise in GPX8." (PMID 38515109, 2024). "This research was driven by the need to gain better understanding of GPX8, considering its importance in cellular processes and multiple roles in cancer biology." (PMID 38607517, 2024). "As regulation of ER stress and H2O2 is critical for rapid proliferation and survival of cancer cells, GPX8 seems to be an important factor linking these basic cancer cell features to the lipogenic phenotype of ccRCC." (PMID 36750850, 2023). "Based on our results, compared to normal tissues, the mRNA of GPX8 was highly expressed in multiple types of cancer, especially in BRCA, COAD, GBM/LGG, HNSC, KIRC, KIRP, LUAD and STAD." (PMID 35402257, 2022). "Combining the results of the two databases showed that GPX8 was upregulated in a variety of cancers including kidney (except chromophobe), stomach, esophagus, cholangio, and brain." (PMID 36061208, 2022). "Despite recent research elucidating the different biological functions of GPx8, its role in regulating radiosensitivity in cancer remains largely unexplored." (PMID 35892591, 2022). "Overall, our pan-cancer analyses of GPX8 have clarified the landscape of GPX8 expression with the clinical prognosis and immune cell infiltration, which provided a predictive biomarker in pan-cancer, especially in the GBM/LGG, KIRC, KIRP and STAD." (PMID 35402257, 2022). "In this work, we aimed to explore the prognostic and immunological role of GPX8 in human cancer and confirm the oncogenic value in GBM." (PMID 35402257, 2022). "In our study, we used immunohistochemistry to determine the expression level of GPX8 in cancer tissues and adjacent normal tissues of 83 patients." (PMID 35712475, 2022). "In this work, we comprehensively investigated the molecular characteristics of the GPX8 gene in 33 different cancers from diverse databases, including TCGA, CPTAC and GEO, and aimed to explore the value of GPX8 in cancer prognosis, progression, and treatment." (PMID 35402257, 2022). "Experiments on cancer HeLa cell line revealed, that GPx8 expression is induced by hypoxia, that silencing of GPx8 impacts membrane lipid composition, and that GPx8 level modulates endoplasmic reticulum Ca2+ concentration and fluxes." (PMID 32878231, 2020). "Nonetheless, further studies are warranted to fully elucidate the role of GPX8 in cancer." (PMID 39833079, 2025). "GPX8 was significantly differentially expressed in 17 out of 21 cancer tissues." (PMID 39833079, 2025). "Additionally, a correlation between GPX8 and poor prognosis have been reported in various cancer types." (PMID 38607517, 2024). "The expression and roles of GPx8 in cancer incidence are unclear." (PMID 38483584, 2024). "Strategies targeting GPx8 may constitute a new therapeutic approach for treating this aggressive form of cancer." (PMID 38483584, 2024). "A correlation between GPx8 and poor prognosis has been reported in various cancer types." (PMID 39125992, 2024). "For example, the interaction between P4HB and GPX7/GPX8 might impact cancer cell responses to oxidative stress." (PMID 38029391, 2023).
cancer (continued). "Given P4HB's role in protein folding and GPX7/GPX8's function in scavenging ROS, their interaction could influence the redox environment crucial for cancer cell survival and proliferation." (PMID 38029391, 2023). "Tissue-specific functions of GPX8 have also been noted in non-cancer settings." (PMID 36750850, 2023). "Finally, our own immunohistochemical (IHC) staining of ccRCC tissues also confirmed the GPX8-tumor grade correlation and higher expression of GPX8 in cancer than in normal tissues." (PMID 36750850, 2023). "However, if and how GPX8 can affect cancer growth through regulation of tissue-specific lipid phenotypes has not been demonstrated." (PMID 36750850, 2023). "Interestingly, recent studies are beginning to shed light on GPX8’s involvement in cancer by showing its roles in the activation of wingless/integrated (WNT) signaling or regulation of invasion and migration." (PMID 36750850, 2023). "The genetic alteration of GPX8 from TCGA cancers was investigated in cBioPortal." (PMID 35402257, 2022). "However, our study first indicated that GPX8 plays a cancer-promoting role in GBM cells, especially in migrative and invasive phenotypes." (PMID 35402257, 2022). "Thus, in this work, we aimed to explore the prognostic and immunological role of GPX8 in human cancer and confirm the oncogenic value in GBM." (PMID 35402257, 2022). "Additionally, a recent study demonstrated GPx8 as a critical player in a metabolic-inflammatory pathway that acts as a robust regulator of cancer cell aggressiveness." (PMID 35892591, 2022). "In addition, according to the median of GPX8 expression in cancer tissues, 83 patients were divided into the high GPX8 expression group and low GPX8 expression group." (PMID 35712475, 2022). "GPX8 was significantly upregulated in 12 of all 20 cancer types compared with normal tissues." (PMID 35712475, 2022). "GPX8 has received extensive attention recently, especially in cancer research, but its function remains unclear." (PMID 36061208, 2022). "Correlation of the GPX8 expression and the clinical characteristic of patients with cancers." (PMID 35402257, 2022). "Furthermore, according to patient data from the Human Protein Atlas, GPX8 exhibits significant differential expression across all cancer types, particularly in glioma, lung cancer, and ovarian cancer (unfavorable), suggesting its potential role as a prognostic marker for these malignancies." (PMID 40563487, 2025). "Based on the results from phosphorylated kinase microarrays, we identified that the primary pathway affected by GPX8 is the AKT pathway, which is a well-established signaling cascade that is implicated in cell proliferation, survival, and growth, usually activated in the progression of cancer." (PMID 38607517, 2024). "Finally, we evaluated the mRNA expression pattern of GPX8 in the remaining 20 cancer types." (PMID 35712475, 2022). "It implied that GPX8 might be a potential target for the diagnosis and treatment of cancers." (PMID 35402257, 2022). "Moreover, we analyzed the expression of GPX8 in several cancers using the GEPIA database." (PMID 36061208, 2022). "In addition to GPX8, the others have been reported to involve in cancer metastasis." (PMID 35978854, 2022). "This study highlights the potential of GPX8 as a prognostic marker in STAD and COAD, providing valuable insight into the development of personalized treatment strategies for cancer patients." (PMID 39833079, 2025). "Among them, GPX8 showed mainly copy number heterozygous amplification in cancers such as ACC, LIHC and DLBC; while in cancers such as LUSC and ESCA, it mainly showed significant copy number heterozygous deletion." (PMID 38515109, 2024). "This, together with the observed downregulation of GPX8 gene (log2FC = −2.27), which functions to combat oxidative stress, might explain the results from the previous study, where decreased proliferation and increased oxidative stress were observed for cancer cells after TOMM34 knockdown." (PMID 36829477, 2023).
cancer (continued). "To confirm the function of GPX8, we selected GBM as a typical type of human cancer for further investigation." (PMID 35402257, 2022). "Additionally, through the enrichment analyses of GPX8-related genes, we recognized the “Glutathione Metabolism”, “Antioxidant Activity” and “Antioxidant Activity” may be the potential mechanism for GPX8 to influence the etiology(ies) and pathogenesis of cancers." (PMID 35402257, 2022). "However, the prognostic potential of GPX8 in pan-cancer remains unclear." (PMID 35402257, 2022). "However, the expression and functions of GPX8 in cancers remain unclear." (PMID 36061208, 2022). "This phenomenon suggests that GPX8 may enhance the stemness of HCC cells, thus we investigated the expression of several typical cancer stemness markers." (PMID 38607517, 2024). "Furthermore, we observed that GPXs family members, including GPX8, commonly exhibit copy number variation (CNV) changes across various cancers." (PMID 38515109, 2024). "The functions of GPX8 in cancers have not been investigated clearly." (PMID 35712475, 2022). "However, although the emerging genes are related to the prognosis, we have never retrieved any report with a pan-cancer analysis of GPX8." (PMID 35402257, 2022). "Furthermore, high GPX8 expression was found to be correlated with a higher degree of CD4+ T cell-infiltrating in COAD and neutrophil-infiltrating in STAD, indicating that GPX8 may play a role in immune evasion in cancer progression." (PMID 39833079, 2025). "Besides, targeting protein degradation has emerged as a strategy in cancer therapy via PROTAC or deubiquitylase enzyme inhibitors, which may also be a potential strategy of targeting GPX8 for LUAD metastasis with the further study of GPX8 degradation in the future." (PMID 35978854, 2022). "However, the functions of GPX8 in cancers have not been explored." (PMID 35712475, 2022).